HMGA1P4 (high mobility group AT-hook 1 pseudogene 4)
Gene: Long non-coding RNA gene on chromosome 9 (128,663,120 to 128,684,991, reverse strand). Ensembl gene ENSG00000234705.
Diseases named in the same sentence as HMGA1P4 in open-access papers:
HMGA1P4 is named in the same sentence as 3 diseases in open-access papers, as found by Europe PMC text mining. Sharing a sentence is not in itself a finding about the gene and the disease. The quoted sentences say what the papers report.
gastric cancer (3 papers, 2020 to 2022). A primary or metastatic malignant neoplasm involving the stomach. "HMGA1P4 is highly expressed in gastric cancer tissues and promotes cisplatin resistance in gastric cancer." (PMID 36212132, 2022). "A limited number of studies revealed that HMGA1P4 was functional in gastric cancer." (PMID 35872920, 2022).
HMGA1P4 also shares sentences with these, for which no sentence is quoted: atherosclerosis (1 paper); tumour (1).